LANCL3 (LanC like family member 3)
Synonyms: FLJ42925
Tractability: Antibody: its Gene Ontology location is reachable by antibodies, with medium confidence. PROTAC: its protein half-life has been measured.
Gene: Protein-coding gene on chromosome X (37,571,569 to 37,684,463, forward strand). Ensembl gene ENSG00000147036.
Subcellular location (Human Protein Atlas): Mitochondria
Gene Ontology:
Biological process: carbohydrate metabolic process; peptide modification
Homologues: Orthologues: chimpanzee LANCL3 (100% identical), macaque LANCL3 (99% identical), rabbit LANCL3 (98% identical), dog LANCL3 (98% identical), pig LANCL3 (98% identical), rat Lancl3 (97% identical), mouse Lancl3 (96% identical), guinea pig LANCL3 (81% identical), tropical clawed frog lancl3 (72% identical), Drosophila melanogaster CG2061 (40% identical). Paralogues in human: LANCL1 (34% identical), LANCL2 (33% identical).
Diseases named in the same sentence as LANCL3 in open-access papers:
LANCL3 is named in the same sentence as 4 diseases in open-access papers, as found by Europe PMC text mining. Sharing a sentence is not in itself a finding about the gene and the disease. The quoted sentences say what the papers report.
cancer (1 paper, 2011). A tumor composed of atypical neoplastic, often pleomorphic cells that invade other tissues. "Among them, those highly correlated with different pathological stages are LANCL3, MFAP2 and PPA1, showing consistent up- and down-regulation, respectively, along with cancer progression." (PMID 21445269, 2011).
infection (1 paper, 2023). The state of being infected such as from the introduction of a foreign agent such as serum, vaccine, antigenic substance or organism. "Similar results were obtained for non-infection associated TashAT2 modulated candidates, with higher expression confirmed for sulphatase 1 (SULF1), Lanthionine synthase C-like protein 3 (LANCL3) and troponin (TNNC1)." (PMID 37276213, 2023).
LANCL3 also shares sentences with these, for which no sentence is quoted: Obesity (1 paper); osteosarcoma (1).